Y_RNA (Y RNA )
Gene: Miscellaneous RNA gene on chromosome 1 (185,266,535 to 185,266,627, forward strand). Ensembl gene ENSG00000252612.
Homologues: Orthologues: chimpanzee Y_RNA (80% identical). Paralogues in human: Y_RNA (77% identical), RNY3 (70% identical), RNY3P1 (70% identical), Y_RNA (70% identical), Y_RNA (69% identical), Y_RNA (68% identical), Y_RNA (67% identical), Y_RNA (66% identical), RNY3P11 (65% identical), RNY3P12 (65% identical), RNY3P16 (65% identical), RNY3P4 (65% identical), and 82 more.